STAT3 (signal transducer and activator of transcription 3)
Diseases named in the same sentence as STAT3 in open-access papers (continued):
Sharing a sentence is not in itself a finding about the gene and the disease.
esophageal cancer (continued). "In this present study, we enriched SFCs and investigated the function and mutual regulation mechanism of STAT3 and miR-181b in esophageal cancer stem-like cells." (PMID 27189061, 2016). "In orthotopic esophageal cancer mouse model, decreased tumor growth and lung metastasis with reduced Ki-67 and phospho-STAT3 expression were observed in mice treated with CYT-Rx20." (PMID 27875549, 2016). "Decreased protein expression of phospho-p85, phospho-AKT, and phospho-STAT3 was observed in esophageal cancer cells after CYT-Rx20 treatment, while the total form of p85, AKT, and STAT3 was not significantly altered by CYT-Rx20." (PMID 27875549, 2016). "Collectively, these data suggest that miR-124 functions as a tumor suppressor in esophageal cancer through, at least partially, targeting STAT3 signaling pathway." (PMID 25928665, 2015). "We therefore investigated the correlation between p-STAT3 levels and clinical outcomes in esophageal cancer patients." (PMID 26553224, 2015). "We retrospectively analyzed the clinical outcomes of patients with ESCC and examined the correlation between p-STAT3 levels and clinical outcomes in esophageal cancer patients." (PMID 26553224, 2015). "As expected, restoring the expression of STAT3 in both esophageal cancer cell lines partially abolished miR-124-mediated tumor suppression." (PMID 25928665, 2015). "Taken together, our results establish a functional link between miR-124 and STAT3 expression in esophageal cancer, demonstrating that STAT3 is directly repressed by miR-124, which subsequently inhibits its downstream signaling pathway." (PMID 25928665, 2015). "Dual-luciferase assays identified that STAT3 is a target gene of miR-124 in esophageal cancer cells." (PMID 25928665, 2015). "Collectively, these findings identified that miR-124 regulates the expression of STAT3 post-transcriptionally in esophageal cancer cells." (PMID 25928665, 2015). "Firstly, we identified the target role of STAT3 in esophageal cancers using Dual-luciferase reporter assays." (PMID 25928665, 2015). "AG490 is a member of the typhostin family of tyrosine kinase inhibitors, which inhibit the JAK/STAT3 signaling pathway in several types of cancer cell, including esophageal carcinoma cells." (PMID 25373392, 2015). "Therefore, phlorizin suppressed oesophagal cancer development by antagonizing the JAK2/STAT3 signaling pathway." (PMID 40761486, 2025). "However, the constitutive activation of this pathway was found to promote the aggressiveness in breast and esophageal cancer, and the elevated phosphorylation levels of JAK1 and STAT3 were linked with the dismal prognosis." (PMID 38095644, 2023). "TRIM29 has been reported to inhibit cytokine production, such as IL6, and TRIM29 knockdown markedly enhanced the production of these cytokines, which could activate STAT3 in multiple tumors, including esophageal cancer." (PMID 37365152, 2023). "However, in the vast majority of cases, patients with esophageal carcinoma (ESCA P = 0.0036 HR = 0.61) with high levels of STAT3 expression had a significantly better median survival time than those with low expression." (PMID 36977736, 2023). "However, in the vast majority of cases, patients with DFS and esophageal carcinoma (ESCA) with high levels of STAT3 expression had a significantly better median survival time than those with low expression." (PMID 36977736, 2023). "STAT3, a gene well known to function in apoptosis and that induces G1-arrest when silenced in esophageal carcinoma, was significantly reduced by miR-323a-3p in all three cell lines, and a functional binding site for miR-323a-3p in the STAT3 3 ́UTR was confirmed by luciferase assay." (PMID 37033189, 2023). "Together, these results demonstrated that STAT3 level is higher in esophageal cancer cells, and STAT3 may play an important role in regulating the proliferation of esophageal cancer cells." (PMID 33390934, 2020).
esophageal cancer (continued). "This suggested that metformin induced apoptosis of esophageal carcinoma cells partly regulated by the Stat3/Bcl-2 pathway, which may have little function on normal esophageal epithelial cells." (PMID 32258099, 2020). "The treatment strategy targeting components of the IL-6/JAK/STAT3 signaling pathway might play a role in optimizing treatment outcomes in esophageal cancer." (PMID 31126307, 2019). "Further, studies also placed STAT3 at a central node in esophageal cancer." (PMID 29636641, 2018). "Knockdown of STAT3 could induce the apoptosis and G1 cell cycle arrest in esophageal carcinoma ECA109 cells, and inhibit the migration ability of cells as well." (PMID 29636641, 2018). "It is reported that STAT3 is highly active in myeloma cell lines, as well as in head and neck squamous cell, breast, brain, gastric, lung, and esophageal carcinomas." (PMID 30186159, 2018). "Based on our results, we concluded that down-regulation of STAT3 could induce the apoptosis and G1 cell cycle arrest in esophageal carcinoma ECA109 cells, and also inhibit the migration ability of cells." (PMID 29636641, 2018). "Given the critical role of NFκB in cell growth and survival, it is conceivable that, in addition to cyclin D1 and c-Myc, NFκB may mediate the effects of STAT3 on esophageal cancers." (PMID 29179470, 2017). "Of note, the cytotoxicity and anti-migratory effect of CYT-Rx20 were enhanced by co-treatment with SC79 (AKT activator) or colivelin (STAT3 activator), suggesting the dependency of esophageal cancer cells on AKT and STAT3 for survival and migration, an oncogene addiction phenomenon." (PMID 27875549, 2016). "Therefore, our current findings suggest that high cellular AKT or STAT3 expression leads esophageal cancer cells to rely on AKT or STAT3 for survival as a result of oncogene addiction." (PMID 27875549, 2016). "To further explore whether miR-124-mediated growth inhibition in esophageal cancer cells via the direct targeting of STAT3, we adopted a “rescue” methodology." (PMID 25928665, 2015). "For esophageal cancer, STAT3 was constitutively activated in cancer tissues, and overexpression of STAT3 could activate esophageal epithelium cells to form tumors in vivo by up-regulating Oct-1." (PMID 25928665, 2015). "Similarly, ectopic miR-125a-5p could potentiate the cytotoxic and apoptotic effects of DDP on esophageal cancer cells through modulating the signal transducer and activator of transcription 3 (STAT3) signaling pathway." (PMID 34881242, 2021). "However, it remains unclear whether proliferation of esophageal cancer stem-like cells (ECSLCs) is suppressed by SNX-2112 with knockdown of STAT3 (shSTAT3)." (PMID 33390934, 2020). "However, the regulatory relationship in esophageal cancer stem-like cells between STAT3 and miR-181b remains unclear." (PMID 27189061, 2016). "However, for esophageal cancer cells, the relationship between STAT3, microRNAs and cancer stem cells remains unclear." (PMID 27189061, 2016). "The fact that STAT3 signaling pathway has been widely reported to be activated in esophageal cancer tissues, and perform important function in the initiation and progression of this tumor make us to speculate that whether miR-124 was involved in its regulation and function." (PMID 25928665, 2015). "Moreover, restored the expression of STAT3 in esophageal cancer cells transfected with miR-124 before, could partially abolished the suppressive effects of miR-124 on the proliferation and invasion of Eca109 cells." (PMID 25928665, 2015). "In esophageal carcinoma, the JAK2/STAT3 signaling pathway can promote cell cycle arrest and mitigate the cytotoxic effects induced by radiation, functioning as a downstream component of the cGAS-STING pathway." (PMID 39975558, 2025). "In esophageal cancer, in vitro experiments have demonstrated that the CXCL12/ACKR3 axis activates the STAT3 pathway." (PMID 38920657, 2024).
esophageal cancer (continued). "Constitutively activated STAT3 and positively regulated PLK1 collectively enhanced proliferation and apoptosis resistance in the esophageal cancer cell line KYSE510." (PMID 38273295, 2024). "In esophageal cancer cells, CPT also reduced the expression of STAT3 and the activation of STAT3 mediated by IL-6." (PMID 38397437, 2024). "The expression of STAT3 was negatively correlated with the MSI in STAD, SKCM, SARC, PRAD, PAAD, HNSC, esophageal carcinoma, and diffuse large B-cell lymphoma, but positively correlated with COAD." (PMID 37724127, 2023). "Inhibition of the STAT3 pathway using AZD9150 weakened the accelerated effects of CXCL12/CXCR7 on the growth and metastasis of esophageal cancer in vitro and in vivo." (PMID 35264069, 2022). "In human esophageal cancer, TRIM44 was involved in the AKT/mTOR signaling pathway and STAT3 phosphorylation." (PMID 33391405, 2021). "In conclusion, our findings indicate that carbon ions inhibit the sustained activation of STAT3 through the JAK2/STAT3 pathway, which inhibits the migration and invasiveness of esophageal cancer cells." (PMID 33330321, 2020). "To uncover the mechanism through which genistein affects cyclical distribution and apoptosis in esophageal cancer cells, we tested the expression levels and phosphorylation levels of JAK1, JAK2, STAT1 and STAT3 in Eca-109 cells." (PMID 32276266, 2020). "In malignant peripheral nerve tumours, STAT3 and HIF-1α promote oncogenic phenotypes, similarly to oesophageal cancer, where STAT3 knockdown was sufficient to block the expression of HIF-1α." (PMID 31947710, 2020). "As STAT3 inhibitors, NSC74859 and Stattic can improve the radiosensitivity of esophageal cancer through the inhibition of hypoxia and radiation-induced STAT3 activation, as well as the expression of HIF1α and VEGF." (PMID 29688867, 2018). "In conclusion, CYT-Rx20 inhibited esophageal cancer cell viability and metastasis in vitro and in vivo through down-regulation of AKT and STAT3 activities." (PMID 27875549, 2016). "In xenograft tumor-bearing mice, CYT-Rx20 significantly reduced tumor growth of the implanted esophageal cancer cells accompanied by decreased Ki-67, phospho-AKT, and phospho-STAT3 expression." (PMID 27875549, 2016). "CYT-Rx20-treated esophageal cancer cells, when co-treated with AKT activator SC79 or STAT3 activator colivelin, significantly suppressed the viability in KYSE70 and TE8 cells." (PMID 27875549, 2016). "Conversely, another study found that STAT3 and MEK1/2 signalling inhibitors have a similar ability to suppress tumorigenesis, and the combination of both inhibitors more potently affected these phenotypes in oesophageal cancer." (PMID 39858048, 2025). "Through suppressing the IL-6/STAT3 pathway and drug transporter ABCC10, let-7, and let-7g/i could restore the sensitivity to DDP and oxaliplatin and promote apoptosis of esophageal cancer cells." (PMID 34881242, 2021). "In esophageal cancer cells, elevated H19 expression promotes EMT and metastasis through activation of the STAT3/EZH2/β-catenin axis, and, interestingly, H19 was directly targeted by let-7c, suggesting a mutual negative-feedback regulation between H19 and let-7c." (PMID 34572067, 2021). "Concerning therapeutic strategies aiming at CAFs, it has been reported that the application of inhibitors for STAT3 and MEK1/2 could suppress tumorigenesis in the organotypic model of esophageal cancer." (PMID 34885115, 2021). "Noteworthily, phospho-STAT3 can be detected in up to 40% of CRC and up to 60% of esophageal cancer." (PMID 33530306, 2021). "Therefore, the aim of the present study was to investigate the relationship between carbon ion inhibition of the proliferation and metastasis of esophageal carcinoma cells and the JAK2/STAT3 signaling pathway." (PMID 33330321, 2020). "Indeed, icariin has been shown to inhibit the growth of human esophageal carcinoma cells by inhibiting the PI3K/AKT and STAT3 signaling pathways." (PMID 29899697, 2018).
esophageal cancer (continued). "Similarly, OCT1 was discovered to be directly regulated by STAT3 to reduce the expression of caspase 9, BAX, and BAD via ERK and AKT activation to boost proliferation and inhibit apoptosis in esophageal cancer cells." (PMID 26433389, 2016). "While a previous study reported the STAT3 mediates PI3K/AKT activation upon interleukin-6 treatment, our study showed a decreased protein expression of phospho-p85, phospho-AKT, and phospho-STAT3 in esophageal cancer cells after CYT-Rx20 treatment." (PMID 27875549, 2016). "Although we did not explore the role of STAT3 in esophageal cancer cells in this paper, it has been widely performed by others." (PMID 25928665, 2015). "Our data show that, in contrast to studies conducted in oesophageal cancer and anaplastic large cell lymphoma, β-catenin does not influence levels of STAT3 protein in CRC cell lines." (PMID 25348333, 2014). "Although a previous work has reported that STAT3 signaling pathway is involved in miR-124-mediated tumor suppression on endometrial cancer cells, it remains open whether or not STAT3 is also be its putative gene in esophageal cancers." (PMID 25928665, 2015). "Therefore, it appears that altered STAT3 activation and subsequent EMT might, at least in part, be responsible for the aggressive tumor behavior in IL-6-positive esophageal cancer." (PMID 23561329, 2013). "However, it is not clear whether STAT3 regulates esophageal cancer stem cells." (PMID 27189061, 2016).
nasopharyngeal carcinoma (107 papers, 2003 to 2025). A carcinoma arising from the nasopharyngeal epithelium. "In B-cell lymphoma miR-1234 was found to repress expression of STAT3 protein an oncogenic transcription factor, and in nasopharyngeal carcinoma found to be positively associated with OS." (PMID 30475821, 2018). "β-Elemene could also inhibit the growth of C666-1 and HNE2 cells (nasopharyngeal carcinoma cells) associated with the inactivation of signal transducer and activator of transcription 3 (Stat3) and the reduced expression of DNMT1 and enhancer of zeste homolog 2 (EZH2)." (PMID 33801899, 2021). "PD-L1 was also induced by latent membrane protein-1 in Epstein–Barr virus (EBV)-associated nasopharyngeal carcinomas (NPC) through JAK3/STAT3 activation." (PMID 29765155, 2018). "The aim of the study was to investigate the effect associated with the protein expression of VEGF, JAK2 and STAT3 on the clinicopathologic characteristics and prognosis in the development and progression of nasopharyngeal carcinoma (NPC)." (PMID 30123088, 2018). "The CENPN/STAT3/USP37 axis is expected to provide a new therapeutic target for nasopharyngeal carcinoma metastasis." (PMID 40458725, 2025). "miRNA-296-5p enhances the drug sensitivity of nasopharyngeal carcinoma cells to cisplatin via STAT3/KLF4 signaling pathway." (PMID 38509141, 2024). "Knockdown of RKIP enhances nasopharyngeal carcinoma invasion and metastasis by activating Stat3 signaling." (PMID 38914697, 2024). "It is necessary to mention that the constitutive activation of STAT3 (JAK/STAT pathway) plays a significant role in nasopharyngeal cancer (NPC) cell proliferation, migration, and invasion." (PMID 38610995, 2024). "LMP-1 is known to induce HER1 signaling via the NFκB and STAT3 pathways, thus playing a crucial role in nasopharyngeal carcinoma tumorigenesis and prognosis)." (PMID 37847488, 2023). "CKMT1A can reduce the arrest of the G2/M phase cell cycle, enhance colony formation rates, lower the apoptosis rate and c-PARP level, and elevate STAT3 phosphorylation levels via CRISPR/Cas9 system in nasopharyngeal carcinoma." (PMID 35077462, 2022). "A previous study showed that β-Ele inhibited the growth of nasopharyngeal carcinoma cells via inactivation of STAT3." (PMID 35909161, 2022). "Previous work has identified the JAK2/STAT3 pathway to be involved in cisplatin resistance of nasopharyngeal carcinoma and epirubicin resistance of NSCLCs." (PMID 34612768, 2021). "Studies have shown that LMP1 mediates the expression of the EGFR in nasopharyngeal carcinoma in several ways, including via the NF-κB pathway and STAT3 activation." (PMID 34578147, 2021). "This study is intended to explore the correlation of IL-6 and JAK2/STAT3 signaling pathway with clinicopathological features and prognosis in nasopharyngeal carcinoma (NPC)." (PMID 34165442, 2021). "Berberine reduces protein levels of the STAT3 in nasopharyngeal carcinoma cells and blocks STAT3 activation induced by IL-6 secreted by tumor-associated fibroblasts." (PMID 33198257, 2020). "Activation of STAT3 suppresses miR-204-5p activities, in turn affecting proliferation and apoptotic resistance in human pulmonary arterial hypertension and nasopharyngeal carcinoma." (PMID 32102656, 2020). "In nasopharyngeal carcinoma cells, miR-124-3p inhibits cell growth and metastasis formation by targeting STAT3." (PMID 31727022, 2019). "For example, activation of Janus kinase 2 (JAK2)/STAT3 pathway has been shown to suppress miRNA-1 expression by inhibiting miRNA-1 promoter activity in nasopharyngeal carcinoma." (PMID 31157242, 2019). "EBV is the most distinct etiological agent for the development of nasopharyngeal carcinoma (NPC), a type of cancer in which STAT3 activation or overexpression is associated with more than 75% of tumors in regions where EBV is endemic." (PMID 29543893, 2018).